RIOK3 (RIO kinase 3)
Diseases named in the same sentence as RIOK3 in open-access papers (continued):
Sharing a sentence is not in itself a finding about the gene and the disease.
infection (continued). "Thus, the rLuc infected cells produce more RIOK3 transcripts early in infection, and alternative splicing ensues, promoted either by cellular regulatory mechanisms or by the virus to blunt the innate immune response." (PMID 33652597, 2021). "RIOK3 was alternatively spliced in HEK293 cells during the course of RVFV strain MP-12 infection." (PMID 35127560, 2021). "The greater increase in RIOK3 X2 variant alternative splicing during rLuc RVFV infection is probably related to the lack of the major virulence factor NSs that effects host transcriptional shutoff." (PMID 33652597, 2021). "Interestingly, the alternatively spliced X2 variant RIOK3 transcript was represented in spliced EST samples collected from both humans and mice, suggesting a conserved functional role outside of the context of infection." (PMID 33652597, 2021). "The researchers found that the infection of HCV altered m6A modification of specific transcripts, including RIOK3 and CIRBP, and the changes in m6A in RIOK3 and CIRBP were partly caused by HCV-induced ER stress." (PMID 36560634, 2022). "Here, we discriminate the specific effects of RIOK3 in both the IFN and inflammatory pathways during RVFV MP12 infection." (PMID 36146870, 2022). "To further investigate effects of knocking out RIOK3 on inflammatory cytokine expression stimulated by TNFα treatment and RVFV MP12 infection, we employed a luciferase reporter construct (p NFκB-Luc) that is specifically driven by activated NFκB." (PMID 36146870, 2022). "In prior work, we discovered that soon after infection with RVFV MP-12, transcription of the kinase, RIOK3 is upregulated, and curiously, the splicing pattern of the RIOK3 mRNA changes rapidly as well." (PMID 33652597, 2021). "Recently we observed that many mRNAs were alternatively spliced upon infection with RVFV, among them RIOK3." (PMID 35127560, 2021). "Here, we show the noncanonical NFκB pathway is activated early during RVFV (MP12 strain) infection and that alternative splicing of RIOK3 occurs specifically during activation of the noncanonical NFκB pathway." (PMID 37515252, 2023). "We found that RIOK3 alternative splicing isoforms were not abundant in the first 7 hours of infection, but significant IFNB expression was detected beginning at 6 hpi." (PMID 35127560, 2021). "RIOK3 protein level, visualized via western analysis, was slightly increased immediately following RVFV infection, followed by a slow decrease out to 48 hours post infection (hpi)." (PMID 35127560, 2021). "Interestingly, infection with other RNA viruses and transfection with nucleic acid-based RIG-I agonists also stimulated RIOK3 alternative splicing." (PMID 33652597, 2021). "Here, we demonstrate alternative splicing of RIOK3 mRNA is associated with activation of the noncanonical NFκB pathway and suggest this pathway is co-opted by RVFV (MP12) to enhance viral success during infection." (PMID 37515252, 2023). "Interestingly, these genes were not enriched for functional categories related to infection and included examples such as RIOK3, CIRBP, PER2, NOC2L, ALCAM, GOLGA3, and others." (PMID 37509095, 2023). "Similarly, infection of HEK293 cells with Tacaribe virus (TCRV), a New World Arenavirus with single-stranded negative sense RNA genome, increased the fraction of RIOK3 X2 variant RNA." (PMID 33652597, 2021). "In the absence of probiotics, infection by V. coralliilyticus caused an increase in expression of the 26S proteasome non-ATPase regulatory subunit 10 protein (PSMD10) and serine/threonine-protein kinase RIO3 (RIOK3), both of which have been found to inhibit NF-kB activation." (PMID 38650950, 2024). "Therefore, expression of RIOK3 X2 during RVFV MP12 infection could be beneficial for the virus, and this might be due, at least in part, to RIOK3 X2 engaging the noncanonical NFκB pathway through supplementing the p100 pool in the infected cell and thereby diminishing the cell’s type 1 IFN response." (PMID 37515252, 2023).
infection (continued). "Furthermore, to assess whether RIOK3 X2′s engagement of the noncanonical NFκB pathway during RVFV MP12 infection affects the IFN response, relative expression of IFNβ was also measured in MP12-infected HEK 293 cells overexpressing RIOK3 X2." (PMID 37515252, 2023).
cancer (9 papers, 2014 to 2024). A tumor composed of atypical neoplastic, often pleomorphic cells that invade other tissues. "Our findings revealed upregulated RIOK3 expression upon glucose deprivation, with RIOK3 knockout significantly reducing cancer cell survival." (PMID 38453884, 2024). "Right open reading frame kinase 3 (RIOK3) has been reported to be involved in cancer invasion and metastasis." (PMID 36505493, 2022). "RIOK3 expression is increased during hypoxic exposure and increases cell migration and invasion in cancer." (PMID 35280808, 2022). "Studies on HeLa cells indicate that human RIOK-3 is a component of the 40S small ribosome subunit and supports cancer cell growth and survival." (PMID 25477034, 2014). "Human RIOK-3 is over-expressed in cancer cells and interacts with caspase-10 to down-regulate NF-κB signaling by competing with receptor-interacting protein 1 (RIP1) and NF-κB-inducing kinase (NIK)." (PMID 25477034, 2014). "In addition, the expression level of RIOK3 increases with hypoxia, which is an important factor in preventing effective radiotherapy and immunotherapy of cancer." (PMID 36505493, 2022). "Since roles for RIOK3 have also been postulated in cancer and the tumor microenvironment, the regulation of RIOK3 splicing represents a potentially compelling area of study in the realm of host–virus interactions as well as other areas of immune biology and medicine." (PMID 33652597, 2021).
tumor (9 papers, 2010 to 2025). "HCV infection increases m6A levels in genes like RIO kinase 3 (RIOK3) and cold‐inducible RNA‐binding protein (CIRBP), enhancing their translation, promoting immune evasion, and boosting tumor cell proliferation." (PMID 40060195, 2025). "The Rio Kinase 3 (RIOK3) significantly influences arginine metabolism in PDAC, thus affecting tumor proliferation, invasion, and metastasis." (PMID 39090094, 2024). "The function of RIOK-3 is different from those of RIOK-1 and RIOK-2 in human cells, with RIOK-3 controlling tumor cell invasiveness, suppressing the activity of NF-κB and supporting type I-interferon production." (PMID 25477034, 2014). "A set of genes including PRPF38A, RIOK3, QSER1, PSMC3IP, ATAD3B, MGC12982, and C20ORF27 were significantly overexpressed in HCC-R tumor tissue with fold changes ≥4 (P = 0.001 to 0.0001)." (PMID 24377043, 2013). "Administration of RIP‐12 inhibited the growth of IMR‐32 cell‐derived xenograft tumors, as evidenced by reduction in tumor volume, weight, and Ki‐67 proliferative activity, along with up‐regulation of NR1D1, RIOK3, FLCN, or FNIP1 as well as down‐regulation of LAMP1." (PMID 40899609, 2025).
RIOK3 also shares sentences with these, for which no sentence is quoted: cervical carcinoma (1 paper); hepatoma (1); infectious disease (1); major depression (1); mental retardation (1); metabolic disorder (1); neuroblastoma (1); neurological disorders (1); Obesity (1); pancreatic ductal adenocarcinoma (1); respiratory syncytial virus infection (1).